FGF19 (fibroblast growth factor 19)
Diseases named in the same sentence as FGF19 in open-access papers (continued):
Sharing a sentence is not in itself a finding about the gene and the disease.
infection (7 papers, 2020 to 2025). The state of being infected such as from the introduction of a foreign agent such as serum, vaccine, antigenic substance or organism. "In conclusion, we identified a group of cytokines, including IL-17C, MMP-10, FGF-23, CCL23, FGF-19 and CXCL5 that are differentially regulated during asymptomatic and mild symptomatic infections and are known to be associated with tissue repair functions." (PMID 35479098, 2022). "After stable infection of FGF19-OE lentivirus into SK-MES-1 and HCC95 cells, which are two relatively not high FGF19-amplified LSQ cell lines, the effects of FGF19 activity on proliferation were measured." (PMID 32111983, 2020). "TGF-α and FGF-19 may be indicators of tissue repair related to the infection." (PMID 35479098, 2022). "To further explore the impact of the FGF19/ANGPTL4 axis on CRCLM, we knocked down FGF15 in CT26‐luc cells (shFGF15) using lentiviral infection before injecting these cells into the portal vein of the mice to establish a CRCLM mouse model." (PMID 39716892, 2025). "Early infection analysis showed eight markers that were elevated (padj<0.05) in the early infection group compared to the unexposed group, namely TGF-α, HGF, FGF-19, TNFSF14, TRAIL, RAGE-binding protein EN-RAGE, uPA and IL18R1." (PMID 41510260, 2025). "Since FGF19 is an intestinal secreted protein, compared with PCT which is an indicator of infection, it is speculated that FGF19 has the advantage of indicating intestinal lesions." (PMID 39296513, 2024).
liver (3 papers, 2015 to 2025). "Levels of multiple proteins, such as interleukin-17A, matrix metalloproteinase-10, and fibroblast growth factor-19, differed (fold-change >1.2; false discovery rate <0.05) between ileal versus colonic IBD." (PMID 39495605, 2025). "Lower preoperative FGF 19 levels may be a predictor for fatty liver improvement after SG." (PMID 31181641, 2019).
gastrointestinal disease (1 paper, 2013). A disease that occurs in the gastrointestinal system, excluding the hepatobiliary system. "This supports the potential therapeutic role of OCA as a novel FXR agonist in gastrointestinal disease with defective FXR activation/FGF19 induction patterns." (PMID 23518683, 2013).
head and neck tumor (1 paper, 2021). "However, we at least provide a principle of concept that the determination of serum MT levels may enable to predict the levels of FGF19 in head and neck tumor tissues, which would be beneficial for FGFR4-based therapeutics." (PMID 33691750, 2021).
urinary tract diseases (1 paper, 2025). "In contrast, neither age (F = 0.842, p = NS), BMI (F = 0.708, p = NS), nor comorbidities such as urinary tract diseases (F = 2.440, p = NS) and joint degeneration (F = 0.034, p = NS) had a significant influence on FGF-19." (PMID 40943671, 2025).
FGF19 also shares sentences with these, for which no sentence is quoted: Hypertension (6 papers); inflammation (3); viral infection (3); androgen excess (2); breast invasive carcinomas (2); diabetic kidney disease (2); immune disease (2); intrahepatic cholangiocarcinoma (2); Pruritus (2); acral melanoma (1); allergic asthma (1); Anxiety (1); Apert syndrome (1); Autoimmunity (1); bacterial infection (1); Bile Acid Synthesis (1); bladder cancer (1); bladder tumors (1); calculus (1); cartilage disease (1); celiac disease (1); cervical cancer (1); cholangitis (1); Cholecystitis (1); cholelithiasis (1); cognitive decline (1); colon adenocarcinoma (1); colonic (1); colonic disease (1); diabetic retinopathy (1).
A further 37 diseases each share a sentence with FGF19 in 1 paper.